TLR4 (toll like receptor 4)
Diseases named in the same sentence as TLR4 in open-access papers (continued):
Sharing a sentence is not in itself a finding about the gene and the disease.
ulcerative colitis (continued). "VSL#3, for instance, was shown to decrease the expression of toll-like receptor 4, nuclear factor kappa B, and inducible nitric oxide synthetase in ulcerative colitis." (PMID 37630845, 2023). "UMB ameliorated acetic acid-induced ulcerative colitis by modulating TLR4/NF-κB-p65/iNOS and SIRT1/PPARγ signaling pathways." (PMID 37483618, 2023). "There was a significant activation of the NF-κB pathway, increased TLR4 expression, and reduced peroxisome proliferator-activated receptor-γ (PPARγ) expression in ulcerative colitis." (PMID 36079895, 2022). "Kuijieyuan Decoction ameliorates intestinal barrier damage in ulcerative colitis by affecting TLR4-dependent PI3K/AKT/NF-κB signaling pathway." (PMID 35717380, 2022). "Kuijieyuan Decoction ameliorates intestinal barrier damage in ulcerative colitis by affecting TLR4-dependent NF-κB signaling." (PMID 35717380, 2022). "The TLR4/NF-κB signal pathway has been reported to be involved in inflammatory responses in central nervous system disease, ulcerative colitis and cancer." (PMID 34887360, 2021). "Studies have shown that TLR4 is slightly expressed in normal intestinal epithelial cells but highly expressed in the mucosa of ulcerative colitis, indicating that the TLR4-mediated signal transduction pathway is an important link in the pathogenesis of UC." (PMID 34803708, 2021). "Other systemic diseases like Crohn’s disease and ulcerative colitis showed increased TLR4 expression." (PMID 34468896, 2021). "A later study showed that HU210 protects the intestinal mucosa in a murine model of ulcerative colitis, most likely through the toll-like receptor 4 (TLR4) and mitogen-activated protein (MAP) signaling pathways." (PMID 34072930, 2021). "KD improved intestinal barrier injury of ulcerative colitis, antioxidant and anti-inflammatory properties by affecting TLR4-dependent PI3K/AKT/NF-κB signaling possibly through the combination of its main compounds, and improving gut microbiota." (PMID 32848725, 2020). "Excessive inflammation is associated with the high expression of TLR4, thereby abnormal stimulation of TLR2 and TLR4 has been found in ulcerative colitis model." (PMID 31949265, 2020). "We conclude that MRS has a protective effect on acetic acid-induced ulcerative colitis in mice via blocking the TLR4/NF-κB/MAPK signaling pathway and promoting the IL-10/JAK1/STAT3-mediated anti-inflammatory response." (PMID 31182999, 2019). "TLR4 expression is upregulated in both Crohn’s disease and ulcerative colitis, and in pediatric IBD patients, higher levels of TLR4 mRNA and protein were found in the inflamed colonic mucosa when compared with non-inflamed controls." (PMID 29438282, 2018). "EGCG can inhibit the intestinal inflammatory response by reducing the severity of ulcerative colitis and maintaining the Th1/Th2 balance through the TLR4/MyD88/NF-κB signaling pathway." (PMID 29404307, 2017). "In pathological situations however, TLR4 is upregulated in both Crohn’s disease and ulcerative colitis, two components of human IBD, leading to pro-inflammatory signaling via NF-κB." (PMID 24278135, 2013). "In theterminal ileum, a significant increase of TLR2 expression and an up-regulation of TLR4 havebeen reported in patients with active ulcerative colitis and Crohn's disease respectively." (PMID 23028414, 2012). "In contrast, pro-inflammatory markers (IL6, CD68, CD15, TLR4) expression is higher in adenocarcinoma tissues respect to the adenoma, the ulcerative colitis and the healthy tissues." (PMID 21059221, 2010). "However, another study in rats using higher doses also demonstrated the therapeutic effect of PC and showed that its anti-inflammatory effects in ulcerative colitis are probably due to inhibition of the TLR4/NF-κB pathway." (PMID 40498951, 2025). "PPAR‐γ could regulate the progression of ulcerative colitis through regulating TLR4/NF‐κB signaling." (PMID 37837628, 2023).
ulcerative colitis (continued). "Further experimental studies may reveal the mechanistic details of these SNPs that trigger the expression of inflammatory cytokines upon modulation of TLR4 mediated immune response in ulcerative colitis patients." (PMID 34724858, 2021). "TLR4 signaling was the subject of therapeutics (target inhibition) in ulcerative colitis (UC)." (PMID 31207873, 2019). "Indeed, there is a report of increased TLR4 expression in the intestinal epithelium of patients with Crohn’s disease and ulcerative colitis." (PMID 24742067, 2014). "Indeed, compared to control normal colonic mucosal samples, there was enhanced expression of TLR-4 in crypt epithelial cells isolated from histologically normal proximal colon of these colectomy specimens with distal ulcerative colitis." (PMID 24828022, 2014). "However, we report for the first time that expression of transcripts for both TLR-2 and TLR-4 was similar in crypt epithelial cells isolated from histologically normal and inflamed parts of colectomy specimens with left-sided ulcerative colitis." (PMID 24828022, 2014). "We have previously shown that most cancers arising in ulcerative colitis patients express TLR4." (PMID 23691015, 2013). "TLR4 expression is up-regulated in both Crohn's disease (CD) and ulcerative colitis (UC)." (PMID 21203467, 2010). "Ganluyin improves dextran sulfate sodium (DSS)-induced ulcerative colitis by enhancing the expression of tight junction proteins, such as Occludin, Claudin-1, and ZO-1, while inhibiting the enteric-origin toll-like receptor 4 (TLR4)/nuclear factor kappa B (NF-κB) pathway." (PMID 39810933, 2025). "Methyl gallate, the active component of Sanguisorba officinalis L., has a therapeutic effect on ulcerative colitis, and its mechanism may be related to regulating polarization of macrophages, inhibiting activation of the TLR4/NF-κB signaling pathway and apoptosis of colon cells." (PMID 36430509, 2022). "In summary, this study demonstrated that FPH not only could inhibit ulcerative colitis via suppressing the LPS/TLR4/MyD88/NF-κB pathway and strengthen the gut barrier via enhancing the antioxidation of the colon but also could protect against secondary liver injury accompanied by ulcerative colitis." (PMID 34966476, 2021). "In addition, the expression of TLR4 was increased in intestinal epithelial cells and dendritic cells of patients suffering of ulcerative colitis and Crohn's disease and in macrophages of inflamed tissues, while mice knockout for TLR4 showed reduced myocardial ischemic injury." (PMID 24733511, 2014). "The activation of TLR4 in colon cells could induce the expression and release of pro-inflammatory cytokines, as seen in the present study, via activation of NF(nuclear factor)-κB, thereby increasing intestinal permeability in ulcerative colitis." (PMID 22073943, 2011). "Furthermore, inhibiting TLR4 can also modulate gut microbiota homeostasis and the MyD88/NF-κB axis in ulcerative colitis, indicating that TLR4 acts not only as a key sensor of innate immunity but may also regulate neuroimmune crosstalk and gut microenvironment homeostasis." (PMID 41346597, 2025). "Collectively, these results indicated that the dual modulation involving TLR4/NF-κB pathway suppression and Nrf2/HO-1 pathway activation underpins the therapeutic superiority of HES-CUR NPs in mitigating ulcerative colitis relative to the other treatments." (PMID 40808691, 2025). "Besides that, polysaccharides isolated from Allium tenuissimum could be potential candidates for ameliorating ulcerative colitis by suppressing the TLR4 (toll-like receptor 4)/MyD88/NF-κB pathway, regulating gut microbiota, and inflammatory cytokines levels accordingly." (PMID 41425624, 2025). "In ulcerative colitis, probiotics reduced the inflammatory factor TNF-α by inhibiting TLR4 expression in colonic tissue." (PMID 37138630, 2023).
ulcerative colitis (continued). "Compared to histologically normal controls, crypt epithelial cells isolated from colonic mucosal samples affected by ulcerative colitis and Crohn's disease demonstrated enhanced expression of TLR-2 and TLR-4 transcripts and cell surface protein." (PMID 24828022, 2014). "Compared to control cells, crypt epithelial cells isolated from active ulcerative colitis and Crohn's disease colonic mucosal samples showed significantly higher expression of TLR-2 and TLR-4 transcripts and protein (on the cell surface)." (PMID 24828022, 2014). "In an acetic acid–induced ulcerative colitis model, MRS also proved its protective effects by blocking the expression of Toll-like receptor 4 (TLR4) and myeloid differentiation primary response 88 protein (MyD88) and attenuating the expression levels of p-NF-κB, p65, p-JNK, p-ERK and p-P38." (PMID 31807906, 2019). "The wild-type (WT), TLR4, TLR2, and IL-10 knockout (-/-) germ-free mice grown were with or without BF colonization for 28 days, and then administered 1% DSS in drinking water for 7 day to induce acute ulcerative colitis." (PMID 28683149, 2017). "It is possible, therefore, that compared to those without IBD, there is enhanced constitutive expression of TLR-4 in crypt epithelial cells throughout the colon of patients with ulcerative colitis." (PMID 24828022, 2014). "Inflammatory mucosal tissue in the intestines of patients presenting with Crohn’s disease (CD) and ulcerative colitis (UC) showed reduces inhibitor of apoptosis protein (IAP) production, which may occur through enhanced TLR4 signaling and increased bacterial translocation into the mucosa." (PMID 34222037, 2021). "The aim of our studies was to investigate the expression of Toll-like receptor (TLR)-2 and TLR-4 (and in some studies TLR-5) in myofibroblasts and small and large intestinal crypt epithelial cells from control patients and those affected by Crohn's disease and ulcerative colitis." (PMID 24828022, 2014).
Hypertension (112 papers, 2012 to 2026). The presence of chronic increased pressure in the systemic arterial system. "Studies have shown that activation of the TLR4/NF‐κB inflammatory pathway can cause vascular dysfunction in hypertension, and inhibition of this pathway can effectively improve vascular function." (PMID 34331512, 2021). "TLR4 contributes to inflammation and oxidative stress and is associated with endothelial dysfunction and vascular remodelling in hypertension." (PMID 34331512, 2021). "Up to date, a growing body of evidence has associated the TLR4/MyD88/NF-κB pathway within the brain with pathological hypertension, whereas RAS and sympathetic nervous system (SNS) are involved in regulating blood pressure." (PMID 33324685, 2020). "Hypertension, a known risk factor for AA, is regarded as a low-grade inflammatory disease and can enhance TLR4 expression and activity." (PMID 30530865, 2019). "Researches described that hypertension is associated with increased Toll-like receptor 4 (TLR4) expression in the PVN of essential and angiotensin II induced hypertensive rats." (PMID 29573749, 2018). "In this study, TLR4 deficiency mice showed blunted response to Ang-II induced hypertension compared to mice with normal TLR4." (PMID 28743964, 2017). "We therefore chose C3H/HeJLps-d mice representing TLR4 deficiency and C3H/HeOuJ with normal TLR4 to study the role of TLR4 in Ang-II-induced hypertension on renal injury and remodeling." (PMID 28743964, 2017). "A handful of previous studies have reported that TLR4 deficiency protects the myocardium in Angiotensin II-induced hypertension in rat and from ischemia/reperfusion injury in mice." (PMID 25879545, 2015). "Based on previous reports from our laboratory and others, out of 13 TLRs, TLR4 can be implicated in the pathogenesis of hypertension." (PMID 25879545, 2015). "Accordingly, the increased cell proliferation and migration induced by Ang II was reversed by TLR4 antagonists, thus suggesting that increased TLR4 expression is functionally associated with structural alterations that can also contribute to hypertension." (PMID 25093580, 2014). "For example, hypertension is associated with end-organ damage, leading to the release of DAMPs that trigger TLR-4 signaling." (PMID 25400647, 2014). "Hypertension is associated with low-grade inflammation, and Toll-like receptor 4 (TLR4) has been shown to be linked to the development and maintenance of hypertension." (PMID 24223475, 2013). "Systemic and neuroinflammation contribute to hypertension pathophysiology by inducing reactive oxygen species (ROS) production and cell damage, triggering the release of damage-associated molecular patterns (DAMPs) that activate Toll-like receptor 4 (TLR4)." (PMID 39144717, 2024). "Recently, in a mouse model of AngII-induced hypertension, TLR4-deficient mice were protected from the AngII-induced renal injury by a robust antioxidant mechanism which was associated with attenuated pro-inflammatory cytokine production, reduced macrophage activation, and decreased fibrosis." (PMID 33810594, 2021). "Finally, in a model of NG-nitro-L-arginine methyl ester (L-NAME)-induced hypertension, inhibition of TLR4 signaling was associated with reduced contractility and enhanced vasodilation in isolated mesenteric arteries." (PMID 33810594, 2021). "Reduced IH-driven hemodynamic alterations could be a further explanation, as TLR4-deficient mice are less susceptible to hypertension." (PMID 25873766, 2015). "In addition to autonomic dysfunction induced through TLR4, recent studies have identified a causative role for ER stress in hypertension." (PMID 25811788, 2015). "Cardiac TLR4 expression level is increased after angiotensin II infusion, and inhibition of TLR4 signaling markedly suppresses Ang II-induced cardiovascular inflammation, endothelial dysfunction, vascular remodelling and stiffness associated with hypertension." (PMID 26556241, 2015).
Hypertension (continued). "Since recent evidence suggests that TLR-4 signaling directly affects vascular contractility and, thus, blood pressure, the release of DAMPs appears both as a causal reason and as a consequence of hypertension." (PMID 25400647, 2014). "We aimed to investigate whether TLR4 activation due to increased activity of the renin-angiotensin system (RAS) contributes to hypertension and its associated endothelial dysfunction." (PMID 25093580, 2014). "TLR4 has been shown to be linked to the development and maintenance of hypertension." (PMID 24223475, 2013). "Previous studies suggest that enhanced expression of TLR4 may be linked with the development and maintenance of hypertension and low-grade inflammation and augmented vascular contractility in hypertensive rats." (PMID 24223475, 2013). "Finally, in a model of aldosterone-induced hypertension, TLR4 activation was associated with the downstream release of several inflammatory mediators leading to tubulointerstitial damage and fibrosis, whereas anti-TLR4 treatment significantly reversed those deleterious effects." (PMID 33810594, 2021). "Thus, enhanced TLR4 activation might be linked to the development and maintenance of hypertension in SLE." (PMID 31694260, 2019). "In addition, TLR4 is also upregulated by Ang II infusion and TLR4 overexpression contributes to the inflammation, endothelial dysfunction, vascular remodelling and stiffness associated with hypertension." (PMID 26556241, 2015). "However, we cannot discard COX-dependent mechanisms associated with TLR4 activation that might contribute to the vascular dysfunction associated with hypertension." (PMID 25093580, 2014). "Therefore, our results suggest that TLR4 is associated with low-grade inflammation in hypertension." (PMID 22233532, 2012). "TLR4 activation was recently demonstrated to be involved in activation of the RAS induced by uric acid in adipose tissue, causing hypertension and increased expression of inflammatory cytokines." (PMID 40179080, 2025). "A previous study revealed that TLR3- TRIF signalling was activated in Ang II-induced hypertension, whereas TLR4-TRIF and TLR3-TRIF signalling was activated in Ang II-induced cardiac hypertrophy." (PMID 41552821, 2025). "Dysregulation of the gut microbiota and barrier impairment during hypertension induces chronic translocation of lipopolysaccharide (LPS) into circulation, causing an imbalance of NOX and antioxidant enzymes through toll-like receptor 4 (TLR4)." (PMID 39867658, 2024). "In human studies, plasma LPS concentration was positively correlated with hypertension, LPS stimulated and increased the expression of TLR4, releasing inflammatory factors to promote the occurrence of hypertension." (PMID 38993521, 2024). "Increasing evidence proposes that the activation of toll-like receptor 4 (TLR4) is closely involved in the inflammatory process and hypertension." (PMID 39682749, 2024). "In response to high-fat diets, TLR4 knockout prevents obesity-induced endothelial dysfunction and hypertension by reducing NOX1/4 and ROS content, lowering inflammatory factors, and increasing eNOS activity." (PMID 39867658, 2024). "Specifically, in experimental models of hypertension, TLR4 has been shown to promote vascular dysfunction and contribute to the pathogenesis of hypertension." (PMID 39764388, 2024). "Another study showed that deleting TLR4 specifically in cardiomyocytes offers protection against Ang II-induced hypertension and cardiac dysfunction by inhibiting proinflammatory cytokines." (PMID 39453113, 2024). "Chronic hypertension affected peripheral monocyte Toll-like receptor 4 (TLR4) expression andIL-17A serum level, while there was a correlation between theIL-17A concentration and the duration of hypertension." (PMID 39484112, 2024).